HDAC1 (histone deacetylase 1)
Diseases named in the same sentence as HDAC1 in open-access papers (continued):
Sharing a sentence is not in itself a finding about the gene and the disease.
tumor (continued). "We also indicated that YY1 was positively correlated with HDAC1 in HCC cell lines and tumor tissues, while there was a reciprocal regulation between YY1 and HDAC1." (PMID 28489564, 2017). "In a previous report it was observed that, in addition to HDAC1/2, HDAC6 is also upregulated in SHH-MB and its targeting leads to a substantial anti-tumor effect in mouse models of SHH-MB29." (PMID 28276480, 2017). "In this study, firstly, we identified two drug-response profiles to HDACi in HCC cell lines, while our results showed that HDAC1 expression was positively correlated with YY1 in HCC cell lines and primary tumor tissues." (PMID 28489564, 2017). "miR-449a has been reported to suppress tumor cell proliferation/growth and survival by targeting CDK6, CDC25A, Sirt1, HDAC1, cyclinD1, WISP2, and c-Met." (PMID 29254139, 2017). "miR-34a, a putative tumor suppressor miRNA that has been shown to repress tumor growth and metastasis, shares identical seed sequences and target genes with miR-449a, such as SATB2, Sirt1 and HDAC1." (PMID 29254139, 2017). "Together, these findings suggest that pharmacological inhibition of HDAC1 and HDAC2 is sufficient for anti-tumor activities in AML." (PMID 28060870, 2017). "Initial genetic dissection of the role of specific HDACs in murine models has revealed that HDAC1 and HDAC2 play redundant and essential roles in tumor cell growth in vitro and in vivo." (PMID 28060870, 2017). "HDAC inhibitors as single agents, via modulation of HDAC1, HDAC3, HDAC8 and HDAC10 function, increased the expression of MHCA and decreased the expression of PD-L1, PD-L2 and ODC on tumor cells." (PMID 29137331, 2017). "In conclusion, in the present study, we demonstrated that HDAC1 and TCF-12 expression were high in tumor samples from patients with in HCC." (PMID 27092878, 2016). "Both HDAC1 and TCF-12 have a high-expression in GBC and Liver-metastasis tissues contrast with Non-tumor tissues." (PMID 27092878, 2016). "Among HDACs 1-10, class I HDACs (HDAC1, HDAC2, HDAC3, and HDAC8) and HDAC9 were more highly expressed in CCA tissues compared with paired non-tumor tissues (P<0.05)." (PMID 27705912, 2016). "Although CoREST1 has been identified in complexes with factors that promote tumor progression, such as LSD1, ZNF217, ZNF198, HDAC1/2 and SIRT1, the role of CoREST1 in tumorigenesis is unclear." (PMID 25793264, 2015). "Our observed profiles for target engagement therefore corroborate the proposed link between HDAC1 and HDAC2 activities in tumour cell proliferation and inhibition of apoptosis." (PMID 26631872, 2015). "A similar analysis in BRCA1 vs BRCA2 tumours highlighted increase in PPI co-expression around the mitotic regulators CDK1, CDC20 and CKS1B and the histone deacetylases HDAC1 and HDAC6; these are known drug targets for which inhibitors have been developed." (PMID 25521701, 2014). "Statistical analysis showed that high HDAC1 or HDAC4 mRNA expression was significantly correlated with advanced clinical stage (P=0.003 or 0.030, respectively) and poor tumor response of patients (P=0.004 or 0.001, respectively)." (PMID 24830600, 2014). "The combination of HDAC1/3 and COX-2 inhibition significantly impaired proliferation of BxPC-3 cells in vitro and stalled entirely the BxPC-3 cells tumor growth onto the chorioallantoic membrane in vivo." (PMID 24040391, 2013). "Our data reveal a crucial function of HDAC1/HDAC2 in the control of lineage specificity and a novel role of HDAC1 as a tumour suppressor in the epidermis." (PMID 24240174, 2013). "HDAC1 and HDAC2 have been shown to be crucial for cell proliferation and are therefore considered as promising targets for anti-tumour therapy." (PMID 24240174, 2013). "Molecular silencing of HDAC1 using small interfering RNA (siRNA) attenuated VPA-mediated regulation of CDKN1A, CDKN1B and LC3-I/II, regression of tumor cell growth and induction of autophagy." (PMID 23866964, 2013).
tumor (continued). "Transcription of the cell cycle regulator p21 is directly regulated by HDAC1 and HDAC2 and is re-activated by HDAC inhibitors in tumor cells." (PMID 21615950, 2011). "R306465 showed potent inhibition of HDAC1 and HDAC8 in vitro and specifically induced histone acetylation in tumour cells." (PMID 18000499, 2007). "Activity towards HDAC1–3 and HDAC8 has been demonstrated to be essential for tumour cell proliferation." (PMID 18000499, 2007). "The pivotal role of HDAC1 makes it an attractive therapeutic target, and HDAC inhibitors may inhibit tumor growth and metastasis by interfering with chromatin remodeling and gene expression regulation." (PMID 40989695, 2025). "Additionally, HDAC1, HDAC6, and HDAC8 contribute to tumor invasion by increasing matrix metalloproteinase-9 (MMP-9) expression." (PMID 40091020, 2025). "HDAC1, HDAC2, and HDAC6-mediated deacetylation of Sp1 has been reported to enhance cell proliferation and stem cell maintenance, which may contribute to tumor progression and TMZ resistance." (PMID 40450300, 2025). "Beyond direct tumor suppression, our work uncovers a novel dual mechanism: SDFZ‐8 not only inhibits HDAC1‐driven oncogenesis but also reprograms the tumor immune microenvironment by activating T cells, enhancing antigen presentation, and reversing macrophage‐mediated immunosuppression." (PMID 41267925, 2025). "HDACs such as HDAC1, HDAC3, and HDAC6 are frequently overexpressed in solid tumors, promoting malignant phenotypes through the repression of tumor suppressor genes, enhancement of epithelial–mesenchymal transition (EMT), immune evasion, and increased angiogenesis." (PMID 41150792, 2025). "Moreover, HDAC1, HDAC7, and HDAC8 are involved in maintaining the stemness of tumor stem cells, promoting TNBC proliferation and migration." (PMID 40091020, 2025). "Notably, the expression of HDAC1 and HDAC2 was comparable between ALK+ tumor cells and other immune cells, including T cells, B cells, and NK cells, suggesting that class I HDACs are abundant in normal and malignant immune-cell subsets." (PMID 40175628, 2025). "While individual knockdown of HDAC1 or PARP1 modestly reduced cell proliferation, simultaneous knockdown resulted in significantly relatively high suppression of cell viability, indicating a synergistic inhibitory effect on tumor cell growth." (PMID 40789065, 2025). "IKAROS can act as a transcriptional repressor via recruitment of histone deacetylase 1 (HDAC1) and chromatin remodeling, however the mechanisms through which IKAROS exerts its tumor suppressor function via heterochromatin in T-ALL are largely unknown." (PMID 40555735, 2025). "Interestingly, HDAC1, HDAC2, HDAC4, and HDAC11 showed a significant upregulation in tumor compared to normal liver tissue." (PMID 39529166, 2024). "Furthermore, the expression levels of histone acetyltransferase P300/CBP and HDAC1 in HNSCC correlate with the malignancy and prognosis of the tumor." (PMID 38983924, 2024). "We found that some HBL and HCC tumor samples have high levels of HDAC1 and Sp5, suggesting that the HDAC inhibitor SAHA could be used to reduce the HDAC1-Sp5 pathway in HBL and HCC." (PMID 39001363, 2024). "We identified several pathways that shifted during transformation, and the transformation might be promoted by epigenetic alterations (such as HDAC10, HDAC1, DNMT3A) within the tumor cells instead of within the tumor microenvironment." (PMID 39353908, 2024). "This suggests that HDAC1 and HDAC8 may have 50 months or even longer impacts on the survival of tumor patients." (PMID 38168914, 2024).
tumor (continued). "Moreover, in colon carcinoma and sarcoma cells, treatment with HDAC inhibitor Entinostat, a class I HDAC1 and HDAC3 inhibitor, led to increase in expression of NKG2D ligand MICA and MICB, enhancing cytotoxicity of NK cells against tumor cells." (PMID 39161385, 2024). "We observed a significant upregulation of class I HDACs (HDAC1/2/3/8) in malignant tissues regardless of the tumor type." (PMID 39063083, 2024). "Furthermore, in the investigation of the tumor microenvironment(TME), it has been observed that Th17 cells possess the ability to recruit HDAC1, resulting in compaction of euchromatin within the proximal promoter region of CD73." (PMID 39144146, 2024). "HRD tumors are enriched with immunogenic epithelial cells, FGFR1+PDGFRβ+ myCAFs, M1 macrophages, tumor reactive CD8+/CD4+ Tregs, whereas HRP tumors are enriched with HDAC1‐expressing epithelial cells, indolent CAFs, M2 macrophages, and bystander CD4+/CD8+ T cells." (PMID 39136172, 2024). "In previous studies, tumor-related genes TNF-α, VEGFA, and c-Myc were also regulated by HDAC1." (PMID 35053925, 2022). "HDAC2 and 3 are frequently expressed at high levels in hormone-receptor negative tumours, while aberrant HDAC1 expression is common in hormone-receptor positive tumours." (PMID 35632748, 2022). "Expression of each of these proliferative markers (PCNA, MKI67, and HDAC1) positively correlated with that of KSR2, indicating KSR2 may promote tumor proliferation." (PMID 35468812, 2022). "To explore the relationship between KSR2 and tumor cell proliferation, we examined co-expression of KSR2 and the proliferating cell nuclear antigen (PCNA), human Ki67 (MKI67) protein, and histone deacetylase 1 (HDAC1)." (PMID 35468812, 2022). "The expression levels of CCND1, VEGFA, AURKB, HDAC1, HSP90AA1, and HSP90AB1 were positively correlated with immune cell infiltration levels, whereas the expression levels of SIRT2 and CASP9 were negatively correlated with the tumor purity of BRCA." (PMID 35845599, 2022). "CDKN1B, FOS, FOXO1, HDAC1, and RB1 were mainly expressed in the nuclear of tumor cells." (PMID 33748162, 2021). "Thus, the levels of HDAC1 and HDAC7 are correlated with tumor characteristics, such as grade and stage." (PMID 34360879, 2021). "Furthermore, HDAC-1, HDAC-2 and HDAC-3 expression levels were positively correlated with tumor proliferative status, assessed as Ki67 labeling index." (PMID 34441281, 2021). "Interestingly, HDAC1 was also found to be overexpressed in CRC58 and promoted tumor angiogenesis by activating HIF1α/VEGFA59." (PMID 34031358, 2021). "miR-204-5p is a tumor suppressor in HNSCCs, which inhibits tumor growth, metastasis, and stemness by suppressing the signal transducer and activator of transcription 3 (STAT3) signaling and EMT via targeting SNAI2, SUZ12, HDAC1, and JAK2." (PMID 33917482, 2021). "On the other hand, HDAC1, HDAC2, and HDAC3 expression was increased in HBV-positive HCCs, in HBx-expressing cells, and in the liver of HBx transgenic mice compared to matching non-tumor tissue, control liver cells, and wild-type mice, respectively." (PMID 34361112, 2021). "This study demonstrates that, given the heterogeneous expression of p62 in subclones within a tumor, combined inhibition of epigenetic modifiers (DNMT1 and HDAC1) reversed the histone pattern and increased p62 expression, which significantly improved the sensitivity to radiation of HN9-R clones." (PMID 33674559, 2021). "Targeting HDAC1/2 inhibits the binding of CoREST with IL-2 and the IFN-γ promoter, thereby promoting their expression, inhibiting the function of Treg, and enhancing anti-tumor immunity." (PMID 34880761, 2021).
tumor (continued). "Indeed, large‐scale analysis of tumor samples illustrates that CBP/p300 are low and that HDAC1, ‐2, ‐3 are highly expressed in primary CRC tumors and CRC cell lines." (PMID 34258881, 2021). "Even exhausted studies in non-stem-tumor-cells (nsTCs), the role of HDAC1 in CRC-SCs maintenance has not received enough attention over the past years." (PMID 33482915, 2021). "In addition, a network of EZH2 and its interacting proteins (UBC, CDK1, HDAC1, SUZ12, EED) was found to participate in miR-26a-mediated tumor progression." (PMID 34381816, 2021). "Because of this epigenetic dysregulation involving overexpression of HDAC1, HDAC2, HDAC3, and LSD1, we anticipate that the 4SC-202, which specifically targets Class I HDACs (HDAC1, HDAC2, HDAC3, HDAC8) and LSD1, may selectively affect ATRT tumor cells." (PMID 32210076, 2020). "CHC displayed selective anti-proliferation potency on tumor cells but not normal LO2 cells as well as exhibited HDAC1/6 suppression effects." (PMID 33536926, 2020). "Collectively, MAKV-8 appears to be an attractive drug candidate for further consideration in CML therapies, especially considering that the inhibition of HDAC1 and HDAC2, upregulated in LSCs versus HSCs from patients, strongly impacts the transcription of proteins essential for tumor cell survival." (PMID 32430012, 2020). "According to the report, HDACs (HDAC1 and HDAC2) are necessary for the growth and survival of RCC tumor cells, and inhibition of HDACs might improve the response of oncologic chemotherapy for RCC." (PMID 33133154, 2020). "Based on the findings pointing to the involvement of HDAC1 in multidrug resistance of AML cells, an AML cell xenograft mouse model was established and used to evaluate the effect of HDAC1 on the tumor growth in the presence of doxorubicin and Panobinostat treatment." (PMID 31358016, 2019). "For instance, HDAC1, which plays a role in cell proliferation, survival, and inhibition of differentiation, shows higher antigenic reactivity in our study, which has been corroborated in CRC tumor studies." (PMID 29505855, 2018). "To determine whether miR-584-5p imparts its tumor-suppressing and VCR-sensitizing effect by downregulating HDAC1/eIF4E3 levels in MB, we first investigated the function of eIF4E3 and HDAC1 in MB." (PMID 30382096, 2018). "IHC (n = 112 tumor and n = 29 adjacent benign prostate tissue) and ELISA (n = 22 tumor and n = 21 adjacent benign prostate tissue) analysis confirmed differential expression of PTEN, HDAC1, and SFPQ." (PMID 30158500, 2018). "MS275 is a selective HDAC1 and HDAC3 inhibitor, it has multiple anti-tumor effects." (PMID 30547810, 2018). "In addition, we found that 17-AAG had a combined effect in the downregulation of HDAC1, HDAC2, the anti-apoptotic gene BCL-2 and tumour survival gene STAT3 in Hep3B cells in combination with Resminostat." (PMID 30035186, 2018). "In many murine tumor models, HDAC1 and HDAC2 blockade inhibits tumor progress and CSC self-renewal." (PMID 30310855, 2018). "HDAC1 has been identified as a direct negative regulator of cyclin-dependent kinase inhibitors (CDKI) such as p21 to promote unrestricted cell proliferation and cell cycle override in human tumor cells and mouse ES cells." (PMID 29951776, 2018). "Furthermore, we measured HDAC1 and YY1 levels in 50 pairs of HCC tissues and paired adjacent non-tumor tissues (ANLTs)." (PMID 28489564, 2017). "Taken together, our results indicate that Hdac1 and Hdac2 do not have a tumor suppressor function in B cells." (PMID 27886239, 2016). "Altogether, metabolomic data suggest that a decreased GPChol/PChol ratio isassociated with high-grade tumors and that the expression of HDAC1,HDAC4 and SIRT1 may influence tumor aggressiveness throughchanges in metabolomic profiles of tumors." (PMID 25791281, 2015).
tumor (continued). "According to this model, complete loss of HDAC1 and HDAC2 is not compatible with cell proliferation, indicating that drugs inhibiting the activities of both enzymes have the potential of anti-tumor agents." (PMID 24449838, 2014). "Finally, using western blot we confirmed that HDAC1, HDAC2, HDAC3 and COX-2 are expressed in the BxPC-3 CAM tumor." (PMID 24040391, 2013). "The influence of HDAC1 and HDAC6 on tumour aggressiveness is controversial." (PMID 18671804, 2008). "Histone deacetylase 1–3 and HDAC8 have been demonstrated to be key for tumour cell proliferation." (PMID 18000499, 2007). "In our hands, however, MS-275 did not inhibit the activity of HDAC1 complexes precipitated from tumour cells and induced cellular H3 acetylation only at very high concentrations." (PMID 18000499, 2007). "For HDACs with a broader deacetylation specificity than SIRT1, such as HDAC1 and HDAC2, no somatic mutations in tumours have been described, but a dysregulated expression seems to be a common feature of human neoplasia." (PMID 16404435, 2006). "Meanwhile, the monotherapy of HDAC1 inhibitor such as romidepsin elevated serum CCL5 rather than intratumoral CCL5, in which the systemic administration increased serum CCL5 could potentially activate metastasis-prone CCR5+ tumor cells." (PMID 40475010, 2025). "While the direct association between HDAC1 and other SUMO-related genes with GBM was not prominent in the current data, this may be due to their indirect or context-specific roles in tumor biology." (PMID 39723246, 2024). "Also, HDAC1, HDAC2, and HDAC3 play a regulatory role in restricting the transcription of STAT3 target genes within another commonly altered pathway, the JAK/STAT pathway, resulting in subsequent epigenetic silencing of tumor-suppressor genes." (PMID 39409979, 2024). "The tumor tissues were then analyzed by Western blotting to detect the different expression levels of proliferation (Ki67 and PCNA), apoptosis (c-Casp3, c-PARP), metastasis (vimentin), related substrate (p-PDH, HDAC1), and cell cycle-related proteins (CDC25A, CDK4, CDK6, and Rb) in each group." (PMID 38948069, 2024). "Moreover, although inhibition of HIF1α, HDAC1, or EZH2 in immune cells can restore immune cytotoxicity, it also paradoxically induces PD-L1 and PD-L2 expression in tumor cells that in turn could weaken anticancer immunity." (PMID 35840558, 2022). "Meanwhile, as an endogenous inhibitor of histone deacetylase 1 (HDAC 1), tumor-suppressive mammary serine protease inhibitor (maspin) was reported to sensitize drug-induced apoptosis with a better therapeutic outcome in CaP, but the relationship between AR and maspin remains unclear." (PMID 33195208, 2020). "A possible explanation is that the simultaneous deletion of Dot1L and Hdac1 results in the generation of a different class of tumor that does not depend on H3K79 methylation but has acquired other, possibly epigenetic, events that allow oncogenic transformation." (PMID 31304633, 2019). "We show that miR-584-5p mediates its tumor suppressor and VCR/IR-potentiating effect by targeting eukaryotic translation initiation factor 4e family member 3 (eIF4E3) and histone deacetylase 1 (HDAC1), thereby affecting cell cycle progression, microtubule dynamics, and DNA damage response." (PMID 30382096, 2018). "On the other hand, tumour barrier functions of replicative stress and DNA damage signalling networks might be lost when HDAC1/HDAC2 are absent or inactivated." (PMID 29472538, 2018). "The HDAC1 inhibitor failed to enhance cytotoxicity in non-tumor primary cells treated with statin." (PMID 28481295, 2017). "Interestingly, in contrast to previous observations in T cells, ablation of Hdac1 and/or Hdac2 in B cells did not lead to spontaneous tumor development." (PMID 27886239, 2016).